PRDX4 (peroxiredoxin 4)
Diseases named in the same sentence as PRDX4 in open-access papers (continued):
Sharing a sentence is not in itself a finding about the gene and the disease.
tumor (49 papers, 2010 to 2026). "Accordingly, the loss of GSN and PRDX4 increases susceptibility to oxidative stress and tumor aggression and requires further study." (PMID 35804959, 2022). "Based on the current research, we discovered low PRDX4 mRNA expression was significantly associated with worse OS in GC patients, suggesting the tumor suppressor role of PRDX4 in GC." (PMID 32382548, 2020). "Cancer cells also actively modulate their oxidative microenvironment by secreting antioxidants, such as peroxiredoxin 4, suggesting tumor-associated oxidative stress may differ for tumor types and stages of their growth." (PMID 32582711, 2020). "Overexpression of PRDX4 and PRDX6 was associated with advanced tumour stage, larger tumour size, higher immune scores, and increased immune cell infiltration." (PMID 41761027, 2026). "This seems to indicate that PRDX4 acts more as a downstream target in the process of tumor progression, directly affecting tumor progression." (PMID 41445793, 2025). "For PRDX4, eight of 11 samples show low staining in tumor tissue, compared to medium intensity in all normal samples." (PMID 37128318, 2023). "We identified that both SRXN1 and PRDX4 genes are upregulated in LUAD tumor tissue and correlated with the cancer development." (PMID 36829926, 2023). "It has been suggested that PRDX4 has a potential role in tumor initiation, progression, chemoresistance against docetaxel, and disease recurrence." (PMID 37719007, 2023). "Conversely, upregulation of E2F targets (e.g., PRDX4, MCM2; FDR = 2.6e-24) and extracellular matrix genes (e.g., COCH, MATN3; FDR = 8.0e-18) were strongly associated with tumor growth and resistance to ICI-4W." (PMID 37433281, 2023). "LncRNA TP53TG1 suppresses the growth and metastasis of tumor cells by regulating the PRDX4/beta-catenin pathway." (PMID 37529698, 2023). "In advanced CRC, PRDX4 plays an important role in the growth, invasion, and migration of tumor cells, indicating that PRDX4 promotes cell growth, cell cycle distribution, and human cancer progression." (PMID 37124724, 2023). "According to the GO results, catalase (CAT), peroxiredoxin-1 (PRDX1), and PRDX4 were related to hydrogen peroxide catabolic process and reactive oxygen species metabolic process, which led to tumor cell apoptosis." (PMID 37124724, 2023). "The transfection of the DLD-1 cells with GSN shRNA and PRDX4 shRNA led to significantly decreased tumor weight in tumor tissues compared with that of the DLD-1 cells (Control shRNA) in mouse xenografts." (PMID 35804959, 2022). "It has been reported that high expression of PRDX4 was related to good tumor characteristics and prognosis of HCC patients, which was inconsistent with our findings and needed to be validated in experiments." (PMID 33771165, 2021). "Given that oxidative stress can activate inflammation, lead to tumor transformation, and modulate tumor progression, the involvement of PRDX4 in tumors has been extensively studied." (PMID 33456675, 2020). "In summary, PRDX4 plays different roles in different tumor contexts, including tumor histological type, tumor stage, and even tumor microenvironment, such as the oxidative stress balance." (PMID 33456675, 2020). "Expression of Prdx4 shRNA was induced by delivering doxycycline through drinking water from the third day of the tumor cell injection." (PMID 22916164, 2012). "From a genomic screening using Mut6 GBM-derived neurospheres, we have identified a putative tumor driver, peroxiredoxin 4 (PRDX4)." (PMID 22916164, 2012). "Successful knockdown of Prdx4 was also demonstrated by a decrease in Prdx4 immunoreactivity among tumor cells in Prdx4 shRNA groups compared to those in control groups." (PMID 22916164, 2012). "Conversely, genes that were under-expressed in tumor versus normal brain in animals fed a SD (Cyba, Noxo1, Prdx4 and Gpx7) were over-expressed in tumor from animals fed a KD." (PMID 20831808, 2010).
tumor (continued). "In contrast to Gpx7 and Prdx4, cytoglobin (Cygb) - which also protects cells against oxidative stress - was more highly expressed in tumor vs. non-tumor tissue in animals fed a SD, as well as in normal brain when mice were fed a KD." (PMID 20831808, 2010). "Consequently, we further validated the tumor-promoting properties of PRDX4 in CRC by in vitro and in vivo assays." (PMID 36969053, 2023). "On the other hand, the Wnt/β-catenin signaling pathway also provides a mechanism for the action of GSN and PRDX4, which might broadly regulate the transcription of other genes and influence the processes relevant to the tumor’s microenvironment and metastasis." (PMID 35804959, 2022). "These unique features of GSN and PRDX4 upregulation in tumor cells may play an important role in the oxidative stress response—an anti-apoptotic function." (PMID 35804959, 2022). "The functional roles of GSN and PRDX4 in tumor growth, migration, and invasion of CRC remain unclear." (PMID 35804959, 2022). "Although many studies have shown that PRDX4 promotes tumor progression, such as the enhancement of invasion or metastasis and the augmentation of proliferation, the role of PRDX4 in tumors is complicated and specific in certain tumor type." (PMID 33456675, 2020). "As different levels of reactive oxygen species (ROS), including H2O2, in tumor microenvironment exert specific effects on tumor, tumor microenvironment may also affect the role of PRDX4 in tumor via the crosstalk between PRDX4 and oxidative stress." (PMID 33456675, 2020). "In our present study, more macrophages emerged in tumor tissue, which may partly explain the effect of PRDX4 overexpression in the promotion of tumor development." (PMID 33456675, 2020). "In this study, the expression of IL-1β was obviously increased in PRDX4 Tg tumor microenvironment." (PMID 33456675, 2020). "Here, we report that peroxiredoxin 4 (PRDX4) is a putative tumor driver." (PMID 22916164, 2012). "We therefore hypothesized that PRDX4 overexpression promotes GBM tumor growth and/or other malignant properties by preventing further ROS accumulation." (PMID 22916164, 2012). "To test whether Prdx4 knockdown affected the growth and/or infiltration of the injected cells, we analyzed asymptomatic mice four weeks after the orthotopic tumor cell injection (n = 3 per treatment group)." (PMID 22916164, 2012). "Prdx4 knockdown in the transplanted GBM cells increased survival of recipient mice by 35% compared to control groups: While the mice in control groups survived on average 55 days after the tumor cell injection, mean survival of the mice with Prdx4 knockdown was approximately 74 days." (PMID 22916164, 2012). "Peroxiredoxin-4, bromodomain-containing protein 2 and Y-box-binding protein 1 potentiated HCC development and tumor invasion via Wnt/β-catenin pathway 29-31." (PMID 37649614, 2023). "Then we explored the relationship between PRDXs and tumor stage and found that only PRDX2, PRDX3, and PRDX4 were significantly correlated with COAD stage." (PMID 36969053, 2023). "After systematic data curation, four upregulated (YWHAB, TXNDC12, MYL6B, SFN) and four downregulated (FN1, PSMB6, PRDX4, PEA15) markers in miRNA-overexpressed tumor secretomes were identified." (PMID 37128318, 2023). "Previous studies have shown that interventional chemotherapy can promote tumor cell apoptosis; inhibit tumor growth, invasion, and metastasis; and improve prognosis by regulating the expressions of VEGF, Caspase-9, TNFAIP8, and Prdx4." (PMID 36476481, 2022). "Noteworthily, this study is the first to determine the roles of GSN and PRDX4 in the migration and invasion of CRC and tumor growth in nude mice xenograft models of cancer." (PMID 35804959, 2022). "The results demonstrated that PRDX1, PRDX4, PRDX5 and PRDX6 were significant difference between tumor and normal tissues, which were also validated in HPA database." (PMID 34246267, 2021).
tumor (continued). "Subsequently, the correlations between PRDXs and immune subtypes, tumor stemness demonstrated that PRDX1, PRDX4, PRDX6 were closely related with type C1, C2 and C6 infiltrates, while tumor stemness scores were positively with all PRDX members." (PMID 34246267, 2021). "Correlations between higher levels of PRDX1, PRDX4, PRDX6 and type 1, 2, and 6 infiltrates (C1, C2 and C6), suggesting the tumor promoting effect of these PRDXs." (PMID 34246267, 2021). "On the other hand, low expression levels of PRDX1, PRDX4 and PRDX6 were correlated with C3 subtypes, indicating that they are potential tumor promoters, similar to pan-cancer results." (PMID 34246267, 2021). "In our study, greater numbers of lung carcinoma tumors and larger tumors were found in PRDX4 Tg mice, accompanied by enhanced macrophage infiltration and the elevated expression of IL-1β and MMP9 in tumor microenvironment." (PMID 33456675, 2020). "The expression of Peroxiredoxin 4 (PRDX4) was up in 28 (87.5 %) tumors and increased 1.92-fold on average, while RNF149 was overexpressed approximately 2.26-fold in one tumor specimen." (PMID 24318988, 2014). "Genes involved in glycolysis (ALDOA, LDHA, PGK1, PFKL, PGM1) and other metabolic processes (GPX4, PRDX4, ACO2, ASPH, IDH2, SQLE, NPC2, SPTSSA) were upregulated in primary tumor cells, suggesting that the metabolism in primary tumors was distinct from that in their matched metastasis." (PMID 39225101, 2024). "Furthermore, the mRNA expression levels of PRDX1, PRDX4 and PRDX6 were closely related with tumor stage of BLCA." (PMID 34246267, 2021). "The effects of PRDX4 knockdown on DNA damage and apoptosis were reproduced in an orthotopic transplantation model, resulting in suppression of GBM growth and spreading at an early stage of tumor development (four weeks after tumor cell injection) in vivo." (PMID 22916164, 2012). "The presence of GFP immunoreactivity in the tumor cells in Prdx4 shRNA group but not in No shRNA group suggests induction of shRNA expression." (PMID 22916164, 2012). "In contrast, the brain sections from the mice with Prdx4 knockdown showed substantially decreased tumor cell spreading and Ki67 staining was not detectable in the ventral regions." (PMID 22916164, 2012).
cancer (41 papers, 2011 to 2025). A tumor composed of atypical neoplastic, often pleomorphic cells that invade other tissues. "The expression of peroxiredoxin-4 (Prdx4; a protein involved in elimination of reactive oxygen species) has been associated with cancer cell stage in lung, breast, and gastrointestinal tract cancers." (PMID 38730628, 2024). "We used online tools to analyze the expression of PRDX4 in pan-cancer, the proteins interacting with it, as well as the amino acid regions and sites to pathogenicity." (PMID 41445793, 2025). "Given the established link between oxidative stress and the advancement of cancer, there has been a thorough investigation into the involvement of PRDX4 in tumors." (PMID 40458080, 2025). "Its upregulation was reported to positively affect the expression of Peroxiredoxin 4 (PRDX4) thus promoting cancer progression by acting as a cytoprotective mechanism against oxidative-stress-induced damage." (PMID 40862737, 2025). "It was found that the expression of PRDX4 in the prostate ranks among the top in pan cancer, accounting for over half of pan cancer." (PMID 41445793, 2025). "Currently, there is limited research on PRDX4 in PCa, but it has been extensively studied in some other cancers." (PMID 41445793, 2025). "We found that the expression of PRDX4 in PCa was higher than that in more than half of the cancer types in pan-cancer." (PMID 41445793, 2025). "Mechanistically, PRDX4 promotes cancer cell proliferation, migration, invasion, and radio resistance, often through pathways such as Akt/GSK3 and by modulating the TME." (PMID 41373732, 2025). "PRDX4 is an antioxidant enzyme situated in the endoplasmic reticulum, exhibits heightened expression in various malignant tumors." (PMID 40458080, 2025). "Knockdown or depletion of PRDX4 in cancer cells leads to reduced proliferation, increased apoptosis, impaired migration and invasion, and heightened sensitivity to radiation and chemotherapy." (PMID 41373732, 2025). "More recently, it has been reported that a Prdx family member, Prdx4, can regulate cancer‐induced osteoclast activation." (PMID 39263840, 2024). "As a potential clinical indicator of CRC progression, PRDX4’s role in cancer biology attracted our attention." (PMID 36969053, 2023). "Further analyses of PRDX4 cellular functions were performed both in vitro and in vivo to validate the cancer SEA database findings." (PMID 36969053, 2023). "The results showed that knocking down PRDX4 dramatically promoted the sphere-forming capability of cancer cells." (PMID 36969053, 2023). "In LNM stage IV of CRC, deregulated GSN and PRDX4 proteins are involved in cancer cell growth and movement, especially invasion and migration." (PMID 35804959, 2022). "When taken together, the identification of GSN and PRDX4 proteins associated with LNM in CRC may not only be used as novel biomarkers for the early prognosis of CRC metastasis but also act as promising targets for the treatment of cancer growth, migration, and invasion." (PMID 35804959, 2022). "We found that the osteoclastogenic factors previously identified as important for cancer‐induced osteolysis, L‐plastin and PRDX4, are released from erythropoietic cells." (PMID 33587325, 2021). "PRDX4 is a PRDX family member which has an exact double effect on cancer cells according to the previous publication." (PMID 32382548, 2020). "Specifically, the observed co-regulation of PRDX3 and PRDX4 has been proposed as an outcome of antioxidant response and oxidative damage in cancer." (PMID 29433420, 2018). "In pre-treatment cancer tissues of poor responders, we was also observed a high protein content for the peroxiredoxin-4 (Prx4)." (PMID 28423701, 2017).
cancer (continued). "It will be interesting to determine if PRDX2 and PRDX4 regulate the aggressive phenotype of cancer cells under prolonged hypoxia." (PMID 26837221, 2016). "Peroxiredoxin-2 and peroxiredoxin-4 in cluster 2, which were up-regulated in many cancers, showed a significant decrease upon OT-treatment for 12 hr but increased to almost basal level after OT treatment for 48 hr." (PMID 23890079, 2013). "Although high levels of PRDX4 expression have been detected in multiple human cancers, the role of this anti-oxidant protein in oncogenesis has just begun to be explored." (PMID 22916164, 2012). "Immediately after, we analyzed the expression of PRDX4 in pan-cancer." (PMID 41445793, 2025). "Some studies suggested that PRDX3 and PRDX4 was overexpressed in PCa of cancer microarray datasets." (PMID 41445793, 2025). "Firstly, we analyzed the expression of PRDX4 in pan-cancer of TCGA database." (PMID 41445793, 2025). "However, PRDX4 overexpression exhibited opposite effects, indicating its role as a cancer‐promoting gene in RCC." (PMID 40458080, 2025). "Although this study points to Prdx4 as a mediator of cancer cell‐induced osteoclast activation, it is currently unclear whether Prdx family members are expressed by osteoclasts and involved in regulating osteoclast activity and function." (PMID 39263840, 2024). "Furthermore, the effect of PRDX4 on cancer cell proliferation in vivo was assessed by injecting sh-Ctrl or sh-PRDX4 cells into nude mice." (PMID 36969053, 2023). "Consequently, a sphere formation assay was utilized to determine the effect of PRDX4 expression level on the stemness of cancer cells." (PMID 36969053, 2023). "The role of PRDX4 in cancer received considerable attention." (PMID 35308531, 2022). "However, peroxiredoxin-2 and peroxiredoxin-4 of cluster 2, the same ubiquitous family of peroxiredoxin-6, which were up-regulated in many cancers, were shown in an upright “V” shape." (PMID 23890079, 2013). "Therefore, PRDX4 targeting can provide an innovative strategy for cancer treatment, utilizing a weakness of cancer cells – regulation of increased ROS level." (PMID 22916164, 2012). "Moreover, SNO of HSPD1 and PRDX4 were detected in SW 480 cells and human cancer tissue." (PMID 37124724, 2023). "In addition, the pharmacogenomic study of the DEPs in GSCA also showed that the downregulation of proteins such as PRDX4, GDI1, and YWHAE and the upregulation of proteins such as CLEC3B, KRT38, KRT37, and HNRNPCL1 were linked to higher sensitivity toward 30 pan-cancer CTRP drugs." (PMID 37900279, 2023). "Moreover, the change in the expression of TUBA1C, PRDX4, LDHC, C7, and KNG1 due to NVA-AA treatment corroborated with the sensitivity provided by CTRP drugs to cancer cells." (PMID 37719007, 2023). "Examples such as ANXA2 and PRDX4 show significant enrichment in the chromatin accessibility of the cancer-specific enhancers compared to the non-malignant cell types, resulting in marked increases in gene expression." (PMID 37685859, 2023). "Growth invasion and migration of cancer cells by GSN and PRDX4 play a more important role in recurrent CRC LNM stage IV than in general stage I, suggesting that GSN and PRDX4 promote cell growth, cell cycle distribution, and motility for the progression of human cancers." (PMID 35804959, 2022). "The potential EC-enriched candidate biomarkers included nicotinamide adenine dinucleotide NADH dehydrogenase (ubiquinone), 1 alpha subcomplex 5 (NDUFA5), peroxiredoxin 4 (PRDX4) and thymopoietin (TMPO), which were highly expressed in cancer cells compared to normal ones." (PMID 28250368, 2014). "Since downregulation of TUBA1C and PRDX4 proteins was observed only in NVA-AA-treated MDA-MB-231 cells, their downregulated expressions might make MDA-MB-231 sensitive to NVA-AA treatment in the same fashion as shown by cancer cells to THZ-2-102-1 treatments." (PMID 37719007, 2023).
cancer (continued). "The mRNA levels of three out of six genes we tested (SLC2A3, GPI, and PDK3) were selectively decreased by PRDX2 and PRDX4 during prolonged hypoxia, suggesting that PRDX2 and PRDX4 may be negative regulators of glucose reprogramming in cancer cells exposed to prolonged hypoxia." (PMID 26837221, 2016). "However, the role of PRDX4 overexpression in radio-resistance of cancer cells or in GBM phenotypes has not been reported." (PMID 22916164, 2012). "We found that PRDX4 is more highly expressed in MBC compared to FBC (log2FC > 1.0), and its expression in cancer-epithelial cells is significantly higher than in the non-malignant cell types." (PMID 37685859, 2023).
cardiovascular disease (5 papers, 2011 to 2021). "PRDX4 has been proposed as a biomarker of oxidative stress and has been associated with high risk of cardiovascular disease (CVD) and CVD mortality." (PMID 24708840, 2014).
infection (5 papers, 2011 to 2023). The state of being infected such as from the introduction of a foreign agent such as serum, vaccine, antigenic substance or organism. "Prior to the infection, B-lymphocytes were the major producers of PRDX4, SEC11C, ERLEC1 and TXNDC5 and all immunoglobulins." (PMID 23094107, 2012). "The expression of PRDX4, SEC11C, ERlEC1 and TXNDC5 decreased in expression in B-lymphocytes after S. Enteritidis infection suggesting a suppression of common B-lymphocyte function and specialization of B-lymphocyte towards immunoglobulin expression after the infection." (PMID 23094107, 2012).
adenocarcinoma (1 paper, 2019). A common cancer characterized by the presence of malignant glandular cells. "The PRDX4 expression was considered to be high when >40% of the adenocarcinoma cells were positively stained." (PMID 31588184, 2019).
respiratory disorders (1 paper, 2019). "Further studies are necessary to elucidate the clinical significance of serum PRDX4 levels in AE-IPF and other respiratory disorders." (PMID 31888585, 2019).